ALK (ALK receptor tyrosine kinase)
Diseases named in the same sentence as ALK in open-access papers (continued):
Sharing a sentence is not in itself a finding about the gene and the disease.
cancer (continued). "Although ALK was detected in 0% to 1.9% of childhood cancers, no ALK inhibitor has pediatric indications." (PMID 33051474, 2020). "Unlike its oncogenic role in cancer, ALK’s potential involvements in humoral as well as cellular immunity were not the center of investigation previously." (PMID 32059449, 2020). "Thus, polytherapy with ALK inhibitor and MEK/ERK inhibitor suppresses cell growth in resistant cancers." (PMID 32344689, 2020). "We postulated that the ALK activation induced NHERF1 tended to be selectively transported into the nuclei, and such mislocalized NHERF1 proteins were likely abolished the normal functions to suppress the growth and survival of cancer cells." (PMID 32164629, 2020). "Thus, anti-ALK antibody response was not limited to ALCL, but also found in cancer patients bearing either ALK fusion or ALK-WT protein expression." (PMID 32059449, 2020). "The discovery of driver oncogenes with aberrant tyrosine kinase activation, such as ALK, ROS1, RET, or NTRK1 gene rearrangement in cancers, continues to change the therapeutic strategies and treatment regimens accompanied with the development of targeted therapies." (PMID 32871626, 2020). "The identification of fusion driver oncogenes with aberrant tyrosine kinase activation, such as ALK, ROS1, RET, or NTRK1 rearrangement in cancers, is largely changing therapeutic strategies accompanied with the development of targeted therapies, especially potent TKIs." (PMID 31399568, 2019). "In cancer cells with EML4-ALK, the transcription of the C-terminal region of ALK depends on the promoter activity of the fusion partner, EML4, which is a housekeeping gene for the stabilization of microtubules during mitosis, by which the C-terminal ALK protein level also becomes elevated." (PMID 30943926, 2019). "Collectively, our results provide novel insights into the molecular basis for the anti-cancer effect of brigatinib and demonstrate the potential of brigatinib for the treatment of ALK-negative cancer." (PMID 31410188, 2019). "In line with this, 4-PBA restored brigatinib-stimulated ER stress in ALK-negative cancer cell lines (A549, Hep3B and Du145)." (PMID 31410188, 2019). "Hence our results suggest that triple or even quadruple drug treatments should be screened (i.e., ALK, MEK, Bim, and PARP targeting) in the quest for even greater and longer-term cancer suppression." (PMID 31827192, 2019). "Our findings imply that appropriate decision-making in terms of anti-cancer drug selection (EGFR tyrosine kinase inhibitors, ALK inhibitors, or intravenous cytotoxic chemotherapy) is possible based on molecular data obtained from EBUS-GS specimens of patients with advanced NSCLC." (PMID 30807604, 2019). "In this study, we demonstrate its anti-cancer effect and the underlying mechanisms in CRC which is ALK-negative." (PMID 31410188, 2019). "The anti-cancer effect reported here is clearly independent of ALK, but through induction of ER stress-mediated apoptosis." (PMID 31410188, 2019). "ALK signaling-independent AXL overexpressed in drug-tolerant cancer cell subpopulations with EMT and CSC features may be commonly involved commonly involved in intrinsic and acquired resistance to ALK-TKIs." (PMID 29930762, 2018). "Because several previous reviews also provide excellent summaries of aberrant ALK forms in cancers, this review does not present additional detailed information on this topic." (PMID 30400214, 2018). "In particular, we validated a new event in EML4, a gene involved in cancer through a fusion with ALK that is not present in MDA-MB-231 cells." (PMID 29571299, 2018). "We were able to extract DNA and perform an exploratory analysis of the cancer gene mutational status on archival biopsy samples from 11 of 16 patients and did not detect EGFR, KRAS or ALK gene alterations in any cases." (PMID 30647837, 2018). "Additionally, in some types of cancers, such as ALCL, the frequency of ALK rearrangements in patients is high." (PMID 30400214, 2018).
cancer (continued). "However, it is still difficult to treat ALK-positive NSCLC because of the development of novel resistance mechanisms and a drug-tolerant cancer cell subpopulation." (PMID 29930762, 2018). "In NBL, a common pediatric cancer, ProTECT analysis identifies a range of intriguing predicted high affinity neoepitope–HLA targets that should be examined in future studies, such as NRAS:Q61K—HLA-A*01:01, including the ALK neoepitopes examined in detail here." (PMID 29441070, 2018). "The different ALK-TKI-resistant model used was derived from a different type of cancer and appeared to be similar to that of our study An AXL inhibitor is a promising drug in current development to treat human cancer." (PMID 29930762, 2018). "NSCLC cancer cells are characterized by the aberrant activation of EGFR, ALK, or cMet27." (PMID 29449529, 2018). "A number of ALK-negative cancer cell lines as well as reactive tonsils were also negative with the same RT-PCR assay." (PMID 29535836, 2018). "The PLR was 41.5 (18.1–95.2), which suggested that patients with cancer had about a 41.5 high chance of being PCR-positive compared to individual without ALK gene rearrangement." (PMID 29088875, 2017). "As both ALK and RAS signal through the MEK/ERK pathway, we sought to evaluate two previously reported inhibitors of ETS-related transcription factors, which are transcriptional mediators of the Ras-MEK/ERK pathway in other cancers." (PMID 28602975, 2017). "Here, we review the biology of ALK and ROS1 and their roles in cancer progression." (PMID 26802023, 2016). "Preclinical data indicated that ASP3026 may have potential therapeutic effects for patients with crizotinib-resistant ALK-positive NSCLC and potentially for patients with other cancer types of ALK-driven tumors." (PMID 26966027, 2016). "When ARMS cells were transfected for 48 h with ALK, MET or NC siRNA, apoptosis was respectively: 15.6, 14.1 and 12.0 % for RH4, and 14.8, 13.9 and 10.2 % for RH30 cancer cells, respectively, showing that single targeting of ALK or MET proteins did not produce notable programmed cell death." (PMID 26445453, 2015). "Although NPM-ALK+ ALCL was the first type of cancer in which ALK was identified, the effects of ASP3026 have not been evaluated in this neoplasm." (PMID 25026277, 2014). "Compared to negatively expressed ALK cases without any staining, these two cases were indeed weakly stained in cancer cells using the VENTANA ALK IHC analysis." (PMID 24422905, 2014). "Although overall frequencies of aberrations at the chromosome arm level do not appear to significantly differ between ALK fusion-positive and -negative tumors, smaller genomic regions including cancer-related genes do show significant variation." (PMID 23289484, 2013). "Among nine cancer-associated mutations that determine sensitivity to ATRA (Notch 1, BCR_ABL, KIT, FLT3, APC, TET2, K-ras, ALK, MLL_AFF1), KRAS, APC, and KIT mutations are associated with resistance to ATRA (only K-ras is shown)." (PMID 23982413, 2013). "Our work suggests that the similarities between ALK and LTK may be exploited for treatment options if LTK is found to have a role in driving certain cohorts of cancer patients." (PMID 22347506, 2012). "Disease outcomes relative to gene expression of ALK, LTK, PTN, and MK in clinical cancer specimen." (PMID 23267434, 2012). "The annual number of publications related to ALK-TKIs in NSCLC has remained consistently high over the past decade, with over 250 articles published annually since 2016, indicating sustained research interest and highlighting it as a prominent area in cancer research." (PMID 40894217, 2025).
cancer (continued). "Furthermore, Alectinib showed a dual inhibition effect on both ALK and HDAC1, and therefore, it may have additional therapeutic value in cancer subtypes involving ALK and HDAC1, such as ALK-rearranged and HDAC1-overexpressing tumors." (PMID 39752394, 2025). "In addition, small subsets of PTCs, namely those with papillary growth pattern, may harbor fusions of cancer-related genes, among which RET, NTRK1–3, BRAF, and anaplastic lymphoma kinase (ALK) are the most frequent." (PMID 40540622, 2025). "Additionally, ALK amplification as a negative prognostic factor has also been reported in certain cancers." (PMID 40234387, 2025). "ALK alterations, namely inversions and intragenic deletions, as well as ALK protein overexpression seen via IHC, commonly co-occur with TFCP2 fusion, and the upregulation of ALK activity leads to increased cell proliferation and migration in multiple cancer types." (PMID 40361368, 2025). "If metastasized cancer cells are negative for the ALK rearrangement, ALK inhibitors might be ineffective for metastatic lesions." (PMID 39781173, 2024). "Given that ALK blockade polarized RNase1-treated macrophages toward an M1-like phenotype and RNase1 upregulated PD-L1 in HCC cells, we asked whether combined treatment with an ALKi and αPD-1 can control cancer cells in vivo in the context of a complex TME." (PMID 38307859, 2024). "Some studies propose that ALK+ cancers may exhibit distinct immunological characteristics compared to their ALK-negative counterparts." (PMID 38397899, 2024). "However, whether used in monotherapy or combination with chemotherapy, ICIs appear to be ineffective in EGFR, ALK, RET, and HER2 driver gene‐positive cancers." (PMID 39184861, 2024). "However, EGF response was not potentiated in drug-treated cancer lines that expressed constitutively active transmembrane ALK mutants." (PMID 39488530, 2024). "We may conclude that the synergy of cancer cell growth suppression is apparent, from the impact of the potency of the combination of alectinib and SHP099 from the beginning of the ALK signalling pathway through multiple steps that encompass the regulation of the cell cycle and apoptosis." (PMID 37339995, 2023). "However, after detailed molecular profiling, the patient was treated with the ALK inhibitor citrozininb in combination with chemotherapy; at the time of writing, they had reached complete cancer remission with no recurrence 3 years after diagnosis." (PMID 37509339, 2023). "We utilized database analysis, cancer cell assays and PDX models and revealed that SYK stratification consistently enriched the population of patients predicted to be responsive to EGFRis and ALKis among those with EGFR-mutant and ALK-translocated NSCLC, respectively." (PMID 37183231, 2023). "This suggests that patient trials co-titrating SHP2 inhibition with ALK inhibition may be a way to produce a specific inhibitory effect on cancer cell growth, whilst minimising toxicity in ALK-negative cells in the body." (PMID 37339995, 2023). "Targeting ALK and EGFR simultaneously may be an effective way to treat these cancer patients." (PMID 36903251, 2023). "Thus, the combination of ALK and SHP2 inhibitors may provide a way to restrict synergistic cytotoxicity to cancer cells only, by reducing the dose of SHP2 inhibitors required for anticancer action and minimising SHP2-dependent systemic toxicity." (PMID 37339995, 2023). "While Myc is one of the most implicated oncoproteins in human cancer, its pathogenetic roles in ALK+ALCL have not been well-defined, although a handful of previous studies have shown that Myc is a downstream target of NPM-ALK via STAT3 signaling." (PMID 37762644, 2023). "The re-sensitising effect that autophagy inhibitors have had on cancer cell lines and mouse models has been shown in a plethora of cancers, including, BRAF-mutant brain cancers and thyroid cancers, bladder cancer, non-small-cell lung cancer (NSCLC) and ALK-positive NSCLC." (PMID 37363731, 2023).
cancer (continued). "Furthermore, cancer-specific WNT inhibitors are under development and could benefit ALK+ ALCL patients." (PMID 35246138, 2022). "Thus, cancer vaccine–mediated immunotherapy and/or inhibition of TOPK kinase function could be beneficial in the treatment of ALK-positive NSCLC." (PMID 36167821, 2022). "Additionally, the combined targeted therapy, including targeted agents (which were against EGFR, ALK, BRAF, IGF-1R, MET(c-MET), VEGF) and antibody–drug conjugate (ADC), as well as cancer vaccines, was among the top three most effective treatment interventions in this study." (PMID 36361201, 2022). "Because the tyrosine kinase domains of ROS1 and NTRK share structural similarity with that of ALK and multiple ALK inhibitors exert inhibitory effects on ROS1 and NTRK kinase activity, we assessed the efficacy of gilteritinib against ROS1 or NTRK fusion using cancer cell lines and Ba/F3 models." (PMID 33627640, 2021). "Considering the relatively long life expectancy and improving prognosis of patients with ALK translocations, this specific patient population should be treated as are patients without cancer and are likely to derive the same benefits from lipid-lowering therapy." (PMID 36645013, 2021). "In addition, because of the lack of systematic strategy at the time to identify patients with rare cancer with a specific genomic characteristic, we did not systematically identify ALK-positive solid tumors." (PMID 34036223, 2021). "Data for CT of other anti-cancer TT studied in elderly have been reviewed (anti-angiogenic treatment, anti EGFR, M-TOR inhibitors, BRAF and MEK inhibitors, C-KIT inhibitors, HER2 targeted therapies, tyrosine kinase inhibitors, or ALK inhibitors) and showed similar results that for younger patients." (PMID 34207200, 2021). "Since all patients included in our study who received ALK-TKIs therapy were diagnosed as ADCs and received ALK-TKIs as all line treatments, so we further performed subgroup analysis in patients with EGFR-TKIs therapy based on pathological type of cancer, and treatment line." (PMID 32299384, 2020). "No ALK antibody activity was detected in non-cancer normal subjects (N = 5)." (PMID 32059449, 2020). "The ALK-specific siRNA resulted in the specific reduction of ALK gene expression in ALCL cells and interference with the fusion protein function, which could be exploited in cancer therapy 4-7." (PMID 32724469, 2020). "Interestingly, STAT3 activation seems to be a general mechanism of acquired resistance since it was also observed in cancer cells driven by diverse kinases, including EGFR, HER2, ALK, and MET, as well as mutant KRAS following treatment with specific inhibitors." (PMID 30622697, 2019). "Interestingly, brigatinib treatment promoted classic ER signaling protein markers (including PERK, p-PERK, IRE1α, p-IRE1α and CHOP) in ALK-negative cancer cell lines (A549, Hep3B and Du145), but not in ALK-positive cancer cells (H3122 and H2228)." (PMID 31410188, 2019). "ALK drives other cancers through mechanisms independent of fusion proteins entirely." (PMID 31366041, 2019). "Interestingly, while portions of I19 appear to have the propensity of being included in the ALK transcripts expressed in some cancer cells, we are not aware of any example in which the inclusion of other ALK introns is described." (PMID 29535836, 2018). "Therefore, ALK and IGF-1R are independent drug targets according to the criterion developed by Bozic and Nowak19,20 in their models of drug combination to overcome cancer resistance, and our results are consistent with their proposal that combination therapy will be more effective than monotherapy." (PMID 29066738, 2017). "Accumulating evidence indicates that ALK activity of EML4-ALK fusion protein mediates tumorigenicity of NSCLC cells via various oncogenic signaling pathways including PI3K/AKT signaling, which is a key regulator of stem-like properties in a cancer stem cell population." (PMID 26517679, 2015).
cancer (continued). "Since TKI treatment of the ALK-translocated NSCLC H3122 cells induced high expression of ALDH1 in vitro and increased tumorigenesis in vivo, it was necessary to ascertain whether this is a general phenomenon in targeted therapy-sensitive cancer cell lines." (PMID 25238228, 2014). "Together, our data indicate that sorafenib can effectively prevent the emergence of resistance in cancer cells addicted to mutant EGFR, but not in cells addicted to other driver mutations frequently found in NSCLC, such as those involving the oncogenes KRAS and ALK." (PMID 40846697, 2025). "Moreover, our hypothesis considered the possibility of redirecting TAMs activity against ALK-positive tumors, particularly through the restoration of phagocytosis of cancer cells with CD47.DEMs blockade, which would eventually prime CTL through the presentation of ALK peptides." (PMID 39767726, 2024). "Consequently, ALK fusion proteins may circumvent anti-EGFR inhibition to activate downstream components of EGFR, thereby promoting cancer cell proliferation and survival, which could explain the possible mechanism of inner resistance to Cetuximab observed in our patients." (PMID 38740834, 2024). "Although this cancer is linked to genetic instability, the DNA mutations targeted for adenocarcinoma therapy, including EGFR mutations and echinoderm microtubule-associated protein-like 4 (EML4)-anaplastic lymphoma kinase (ALK) translocations, are essentially absent in LSCC." (PMID 33799513, 2021). "Overall, the occurrence of the ALK-translocation in lung AC of never-smokers clearly indicated that the patho-mechanism is based on a single genetic driver rather than on an accumulation of genetic lesions in a variety of cancer genes, as it is the case in smoking-related AC." (PMID 30744199, 2019). "However, it remains unclear if brigatinib has alternative model of action to exert antitumor effect in ALK-negative cancers." (PMID 31410188, 2019). "Moreover, as a hypothesis-generating aim, we explored the correlation between p16Ink4A status and Ki67 as well as the most common molecular aberrations in well-known targetable cancer genes, such as epidermal growth factor receptor (EGFR) and anaplastic lymphoma kinase (ALK)." (PMID 26674347, 2015). "LTK is highly homologous to ALK, a tyrosine kinase that can be aberrantly expressed by cancer cells, and importantly, LTK, but not ALK, is expressed in the lung and small intestine." (PMID 42263913, 2026). "Unlike EGFR and HER2 inhibitors that target receptor tyrosine kinases located on the cell surface, ALK, BRAF/MEK, and PI3K/AKT/mTOR inhibitors act on non-receptor kinases in intracellular signaling pathways critical for cancer cell proliferation and survival." (PMID 40872476, 2025). "A novel ALK isoform, namely ALKATI, was found in approximately 11% of melanoma cases and sporadically in other cancer types but not in normal tissues." (PMID 38606358, 2024). "The results showed that VH20-OKT3-Fc mobilized the T cell killing of ALK-positive IMR-32 and SH-SY5Y cells with IC50s of 0.1 nM and 0.15 nM, respectively, while without killing of ALKnegative SK-N-AS cancer cell." (PMID 38804307, 2024). "In contrast, in the context of ALK gene fusion positive cancers (2x NSCLC, 1x esophagus, and 1x soft tissue), all recommendations (n = 4) for ALK inhibitors were clinically translated, irrespective of the level of evidence." (PMID 38136436, 2023). "PI3Kβ inhibition blocks ALK‐inhibition‐induced cytoprotective reactivation of EGFR signaling, enhancing the cytotoxic effect on both epithelial‐ and mesenchymal‐phenotype cancer cells without affecting normal lung epithelial cells." (PMID 36423211, 2023). "Furthermore, these studies used either experimental compounds (e.g., 4–4-dimethylaminostyryl-N-methylpyridinium (ASP+) and MPP+) or non-cancer drugs (e.g., metformin) as substrates, which may not be suitable to predict pOCT-mediated ALK drug interactions due to substrate-dependent inhibition." (PMID 37765282, 2023).